FABP4 (fatty acid binding protein 4)
Diseases named in the same sentence as FABP4 in open-access papers (continued):
Sharing a sentence is not in itself a finding about the gene and the disease.
liver disease (8 papers, 2017 to 2025). "Future studies are warranted to evaluate the release of FABP4 from different depots and the interaction of liver disease progression in its association with TG levels." (PMID 36769659, 2023). "Although FABP4 correlated significantly with platelet count increase (ρ = −0.48, p = 0.0097) and AST decrease (ρ = −0.45, p=0.0153), those correlations were weaker than the correlation with both composite scores, suggesting that FABP4 levels are associated with the reduction in liver disease." (PMID 32034167, 2020). "Furthermore, the associations with sCD163 and FABP4 warrant further investigation into the role of macrophages in residual liver disease and fibrosis resolution after viral clearance." (PMID 32034167, 2020). "The persistently affected genes Lama5, Gtse1, Fabp4, and Bcl6 possess the potential to be therapeutic targets for liver disease induced by AFB1." (PMID 35783385, 2022). "Finally, we find a significant association between baseline levels of FABP4 and subsequent reduction in APRI and FIB-4 measurements during DAA treatment, suggesting a link between FABP4 plasma levels and liver disease reduction." (PMID 32034167, 2020). "FABP4 may be a marker of psoriasis, and FABP3 may be associated with inflammation or liver disorders in psoriatic patients." (PMID 27864793, 2017). "The persistently affected Lama5, Gtse1, Fabp4 and Bcl6 gene can be potential target genes for the treatment of AFB1 induced liver diseases, but their effectiveness needs to be further explored in experiments." (PMID 35783385, 2022). "Since circulating FABP4 was consistently found to be raised in relation to liver disease progression this might imply that fatty liver could contribute significantly more than SAT to FABP4 serum levels during MAFLD progression." (PMID 36769659, 2023). "In addition, MASLD patients showed a substantial increase in serum FABP4 levels compared with those without liver disease, and this upregulation persisted in MASLD-HCC patients." (PMID 41392988, 2025). "As FABP4 does not contain any secretory signal sequence in its structure, alternative mechanisms, including microvesicles formed by budding from the cell plasma membranes, may be involved, as already described in liver fibrogenesis and portal hypertension." (PMID 30575815, 2019).
non-alcoholic fatty liver disease (8 papers, 2014 to 2025). "We also analyzed FABP4 and SREBP1 mRNA expression, which were linked to the expression of genes responsible for de novo hepatic lipogenesis, lipid storage, and nonalcoholic fatty liver disease pathogenesis." (PMID 33401717, 2021). "Dysregulation was established for FABP3 in cardiovascular disorders, FABP1, FABP2, FABP4 and FABP5 in non-alcoholic fatty liver disease and FABP5 and FABP7 in cancer." (PMID 30386187, 2018).
triple-negative breast carcinoma (8 papers, 2014 to 2025). An invasive breast carcinoma which is negative for expression of estrogen receptor (ER), progesterone receptor (PR), and human epidermal growth factor receptor 2 (HER2). "In a prognostic analysis of all invasive breast cancers according to molecular subtype, FABP4 positivity (p = 0.023) and CPT-1 positivity (p = 0.027) were associated with a shorter DFS among triple negative breast cancers (TNBCs)." (PMID 28124996, 2017). "FABP4 also plays a critical role in the metastasis and stromal interaction of MDA-MB 231, triple-negative breast cancer cells (TNBC)." (PMID 36114448, 2022). "Serum FABP4 levels are negatively correlated with overall survival in patients, and its overexpression promotes lipid uptake via CD36 synergy, activating the STAT3 pathway to induce epithelial-mesenchymal transition (EMT) and stemness in triple-negative breast cancer (TNBC)." (PMID 40717587, 2025).
type 1 diabetes mellitus (8 papers, 2014 to 2025). A chronic condition characterized by minimal or absent production of insulin by the pancreas. "Serum FABP4 is elevated in patients with type 1 diabetes and their first-degree relatives and is closely associated with islet autoantibodies." (PMID 33690220, 2021). "In humans, circulating FABP4 level is elevated in patients with type 1 diabetes as well as their FDRs and is closely associated with the titers of islet autoantibodies." (PMID 33690220, 2021). "Furthermore, serum FABP4 concentrations were significantly increased and independently associated with poor glycemic control in Chinese children with type 1 diabetes and also predict pre-eclampsia in women with type 1 diabetes." (PMID 33690220, 2021). "Furthermore, these associations remained significant after adjustment for age and BMI, suggesting that elevated FABP4 may be causally involved in autoimmune destruction of β cells in patients with type 1 diabetes." (PMID 33690220, 2021). "A study reported that FABP4 accelerates the onset of type 1 diabetes in NOD mice by inducing the polarization of proinflammatory macrophages and their infiltration into pancreatic islets." (PMID 40716098, 2025). "Here we show that circulating fatty acid binding protein 4 (FABP4) level was significantly elevated in patients with type 1 diabetes and their first-degree relatives and positively correlated with the titers of several islet autoantibodies." (PMID 33690220, 2021). "In the present study, we measured the dynamic changes of circulating FABP4 in patients with type 1 diabetes and their first-degree relatives (FDRs) and interrogated its relationship with autoantibody positivity and β cell autoimmunity in these subjects." (PMID 33690220, 2021). "Circulating FABP4 level in patients with type 1 diabetes was significantly higher than in healthy control subjects (median 8.7 [IQR 7.1–12.1] vs. 5.0 [3.7–6.8] ng/mL; P < 0.001)." (PMID 33690220, 2021). "In the present study, we identified FABP4 as an early mediator in the pathogenesis of type 1 diabetes through its actions in islet macrophages." (PMID 33690220, 2021). "Taken together, these findings suggest that augmented TLR/FABP4 signaling axis might be an important link between innate and adaptive immune crosstalk during the onset and progression of insulitis and type 1 diabetes." (PMID 33690220, 2021).
endometriosis (7 papers, 2014 to 2025). The growth of functional endometrial tissue in anatomic sites outside the uterine body. "Effective inhibitors of ROS related to endometriosis are vitamins C and E, astaxanthin, fatty acid-binding protein 4, cerium oxide nanoparticles (nanoceria), osteopontin, sphingosine 1-phosphate, N-acetyl-L-cysteine, catalase, and a high-antioxidant diet." (PMID 40722981, 2025). "Up-regulation of sPLA2IIa and FABP4 gene expression in ectopic versus matched eutopic endometrium from endometriosis patients was reported in previous studies." (PMID 25709631, 2014). "The aim of the present study was to investigate the effects of ω-3 and ω-6 fatty acids intervention on the levels of cellular FABP4 and extracellular sPLA2-IIa in cultured ectopic and eutopic endometrial cells from patients with endometriosis." (PMID 25709631, 2014). "The present study was designed to assess the cellular FABP4 and extracellular sPLA2-IIa in cultured ectopic and eutopic endometrial cells from endometriosis cases under treatment with balanced and high ratios of ω-3 and ω-6 PUFAs." (PMID 25709631, 2014). "More relevant studies are encouraged to know the potential effect of increased cellular FABP4 and extracellular sPLA2-IIa on endometriosis." (PMID 25709631, 2014). "Conversely, the downregulation of FABP4 expression by miR-455 treatment significantly reduced oxidative stress and apoptosis in a human endometrial stromal cell line (HESCs), suggesting the potential role of FABP4 in the development of endometriosis by inducing oxidative stress." (PMID 37628833, 2023). "Moreover, overexpression of several genes including Cyp2r1, Fabp4, Mrc1, and Rock2 has been shown in the liver and visceral adipose tissue of endometriosis cases." (PMID 34806344, 2021). "Therefore with respect to the growth inhibitory action of FABP4, it is likely the production of FABP4 in endometriosis has an antiproliferative effect." (PMID 25709631, 2014). "ω-3 PUFAs may increase the level of cellular FABP4 and extracellular sPLA2-IIa in ectopic endometrial cells, since sPLAIIa and FABP4 may affect endometriosis via several mechanisms." (PMID 25709631, 2014). "It was also shown that miR-455-induced downregulation of FABP4 resulted in a significant reduction in apoptosis and oxidative stress in a human endometrial stromal cell line (HESCs), suggesting that FABP4 may have important roles in the development of oxidative stress-induced endometriosis." (PMID 40429934, 2025). "Overall, it appears that sPLAIIa and FABP4 could affect endometriosis via different mechanisms." (PMID 25709631, 2014). "However, no clinical study has yet determined the circulating FABP4 levels in patients with endometriosis." (PMID 37628833, 2023).
idiopathic pulmonary fibrosis (7 papers, 2022 to 2026). Idiopathic pulmonary fibrosis (IPF) is a nonneoplastic pulmonary disease that is characterized by the formation of scar tissue within the lungs in the absence of any known cause. "Immunohistochemical staining showed that LIRI increased TGF‐β expression in AAV‐shCtl mice, while AAV‐shFabp4 treatment significantly reduced TGF‐β levels, indicating that FABP4 knockdown attenuates pulmonary fibrosis." (PMID 41454478, 2026). "A recent study suggests that expression of Fcn1, Spp1, and Fabp4 is enhanced in monocyte-derived, pro-fibrotic, and normal alveolar macrophage populations of idiopathic pulmonary fibrosis." (PMID 35892659, 2022). "FCN1, FABP4, and SPP1 macrophages are involved in the pathogenesis of lung fibrosis; SPP1 macrophages demonstrate upregulated expression in both SSc-ILD and IPF." (PMID 38937794, 2024). "Furthermore, a specific antifibrotic role for FABP4 as a chaperone of nitro-fatty acids (NO2-FA) is emerging, and a recent study demonstrated reversal of bleomycin-induced lung fibrosis in a mouse model with administration of the NO2-FA nitro-oleic acid." (PMID 37894784, 2023).
melanoma (7 papers, 2020 to 2025). A malignant, usually aggressive tumor composed of atypical, neoplastic melanocytes. "However, fatty acid transporters such as CD36 and FABP4 were upregulated in metastatic melanoma compared to primary melanoma, suggesting increased fatty acid uptake activity." (PMID 37849907, 2021). "We examined whether adipocytes cocultured with melanoma cells demonstrate decreased expression of adipocyte differentiation markers such as leptin, resistin, adiponectin, and fatty acid binding protein (FABP4) by assessing the expression of these genes in the cells." (PMID 37481560, 2023). "The expression of CD36, MARCO, FABP4, FABP6, and FABP7 in melanoma samples and healthy skin biopsies is visualized, according to data retrieved from the IST Online database." (PMID 32209538, 2020). "Furthermore, young-MFP-melanomas expressed higher levels of FABP4, CPT1a, and CD36 than aged-MFP-melanomas validating that the young-MFP is an environment that enhances lipid metabolism in melanoma cells." (PMID 40280124, 2025). "We noticed that mature adipocytes express a high level of selected adipokines (leptin, adiponectin, resistin), lipid transport protein (FABP4), and enzymes related to lipid synthesis (FADS, SC4MOL, FASN), while their levels decrease in adipocytes cocultured with melanoma cells." (PMID 37481560, 2023).
osteoarthritis (7 papers, 2020 to 2025). A noninflammatory degenerative joint disease occurring chiefly in older persons, characterized by degeneration of the articular cartilage, hypertrophy of bone at the margins and changes in the synovial membrane. "Lately, new roles in cancers 40 and osteoarthritis 41 have also been associated with FABP4, indicating the versatile activities of FABP4." (PMID 32896039, 2020). "Regarding Fabp4 (FC = 2.85), recent studies have shown that it is increased in chronic inflammatory diseases such as osteoarthritis and in cellular models of inflammation, which have shown that its knockdown can suppress inflammation and oxidative stress by inhibiting the NF-κB signaling pathway." (PMID 36839217, 2023). "Although by using FABP4 KO mice, previous studies suggested that FABP4 may play a role in several diseases such as cisplatin-induced AKI, cerebral ischemia injury, and osteoarthritis, while the cell type responsible for disease pathogenesis was difficult to clarify." (PMID 35410456, 2022).
preeclampsia (7 papers, 2018 to 2023). Preeclampsia is a hypertensive disorder of pregnancy that is characterized by new-onset hypertension with proteinuria presenting after 20 weeks of gestation, and depending on mild or severe forms may initially present with severe headache, visual disturbances, and hyperreflexia. "FABP4 involves preeclampsia’s pathogenesis via different pathways associated with insulin resistance, inflammation, and dyslipidemia." (PMID 35126178, 2021). "A nested case-control study detected markedly increased maternal serum FABP4 levels at 8 to 13 weeks of gestation in subjects who were eventually diagnosed with preeclampsia, suggesting that FAPB4 is a potential predictive biomarker for PE." (PMID 37628833, 2023). "It has also been reported that maternal FABP4 levels are elevated in preeclampsia, even before the clinical onset of the disease." (PMID 30857223, 2019). "The level of the second trimester plasma FABP4 in the preeclampsia GDM group was significantly higher than that of the patients with only GDM." (PMID 30857223, 2019). "Fatty acid-binding protein 4 (FABP4) has been proposed to be a potential predictive factor of gestational hypertension or preeclampsia (GH/PE) because of its integrating metabolic and inflammatory responses." (PMID 29394285, 2018). "A previous study reported that maternal FABP4 concentrations were elevated in preeclampsia, even before its clinical onset in both the normal population and women with T1DM." (PMID 29394285, 2018). "Corroborating with our results, recent studies also showed that FABP4 inhibition could suppress saturated-fatty-acid-induced skeletal muscle inflammation and preeclampsia inflammasome activation." (PMID 35410456, 2022). "Maternal plasma FABP4 is independently related to the development of preeclampsia." (PMID 35126178, 2021). "Interestingly, pregnant women with high FABP4 levels in first trimester were more likely to develop preeclampsia." (PMID 34372761, 2021). "A recent study reported elevated serum FABP4 levels in women with preeclampsia." (PMID 29394285, 2018). "In the non-pregnant state, FABP4 is associated with risk factors of preeclampsia, such as obesity, hypertension, and diabetes mellitus." (PMID 29394285, 2018). "FABP4 is a potential predictive factor of the subsequent GH/PE in GDM patients, but it may not be specific for predicting preeclampsia." (PMID 29394285, 2018).
serous ovarian cancer (7 papers, 2017 to 2025). "In serous ovarian cancer, the overexpression of fatty acid binding protein 4 leads to an increase of glycerolipids, glycerophosphoethanolamines, glycerophosphoinositols such as LysoPE, LysoPG, and LysoPI." (PMID 37775701, 2023). "More studies have shown that high FABP4 expression in advanced serous ovarian cancer cells reduces the rate of metastatic tumor growth in mice." (PMID 35646090, 2022). "We obtained tumour microarrays of 16 low-grade and 51 high-grade serous ovarian carcinomas and determined expression of FABP4 protein in tumour vessels and tumour epithelial cells." (PMID 27568980, 2017). "The results revealed that FA metabolism regulators including FABP4, FABP5, and PPARγ are involved in biological aspects in two EOC cell lines, AMOC-2 cells established from ovarian serous adenocarcinoma (OSC) and ES2 cells established from OCCC." (PMID 40429934, 2025).
left ventricular hypertrophy (6 papers, 2018 to 2024). Enlargement of the LEFT VENTRICLE of the heart. "FABP4 was directly associated with cardiac diseases, including left ventricular hypertrophy, systolic and diastolic cardiac dysfunction." (PMID 30969942, 2019). "In humans, FABP4 has been identified as a biomarker for cardiac metabolism and physiopathology including left ventricular hypertrophy and both systolic and diastolic cardiac dysfunction." (PMID 30517173, 2018). "Interestingly, abnormalities in ECG especially left ventricular hypertrophy, conduction block, and arrhythmia were only demonstrated in patients with higher FABP4 levels." (PMID 34987673, 2021). "However, left ventricular hypertrophy (8.7%), conduction block (8.7), and arrhythmia (4.3%) were only seen in patients with higher serum FABP4 levels." (PMID 34987673, 2021).
lung adenocarcinoma (6 papers, 2014 to 2025). A carcinoma that arises from the lung and is characterized by the presence of malignant glandular epithelial cells. "In this study, scRNA‐seq revealed heterogeneous cellular clusters within lung adenocarcinoma, including Epithelial, Macro_FABP4, T cells, B/Plasma, and CD8_NK_like populations, underscoring the complexity of the tumor microenvironment." (PMID 40767620, 2025). "Among them, CRABP2, KAT2A, BIRC5, ABCC3, PLK1, IGHG1, and EPCAM were upregulated in lung adenocarcinoma samples, while FABP4 was downregulated in lung adenocarcinoma samples." (PMID 35909589, 2022). "The expressions of PDK4, FMO2, and FABP4 are significantly downregulated in lung adenocarcinoma compared to normal lung tissue in several datasets, and this phenomenon was also observed in GSE10072 array." (PMID 29285217, 2017). "The analysis of the effects from each gene expression on survival outcome indicated that 6 genes (AGR2, SPDEF, CDKN2A, CLDN3, SFN, and PHLDA2) play oncogenic roles, and 7 genes (PDK4, FMO2, CPED1, GNG11, IL33, BTNL9, and FABP4) act as tumor suppressors in lung adenocarcinoma." (PMID 29285217, 2017). "Our data showed that FABP4 may have tumor suppressor effects in lung adenocarcinoma." (PMID 29285217, 2017). "According to the immune staining intensity comparisons provided by the HPA database, the expression levels of FABP4, GDF10, and LTBP4 were higher in normal samples, while the expression level of CBLC was higher in lung adenocarcinoma samples." (PMID 40766337, 2025). "In cancer patients with lung adenocarcinoma, the survival curve analysis indicated that the population with higher expression of PDK4, FMO2, or FABP4 is correlated with better survival rates." (PMID 29285217, 2017).
osteosarcoma (6 papers, 2020 to 2025). A usually aggressive malignant bone-forming mesenchymal neoplasm, predominantly affecting adolescents and young adults. "A recent study utilizing single‐cell RNA sequencing revealed a significant presence of FABP4+ macrophages in lung metastatic osteosarcoma lesions." (PMID 39658531, 2024). "A proinflammatory FABP4+ macrophages infiltration is noticed in lung metastatic osteosarcoma lesions." (PMID 33303760, 2020). "In addition, the study revealed that the proinflammatory fatty acid-binding protein 4+ macrophage infiltration was identified in lung metastatic osteosarcoma lesions." (PMID 35515114, 2022).
pancreatic cancer (6 papers, 2022 to 2025). "Similarly, high expression of FABP4 is considered to be associated with poor prognosis in breast, prostate, ovarian, and pancreatic cancers." (PMID 36532833, 2022). "In pancreatic cancer, FABP4 facilitates the movement, invasion, and spread of cancer cells by influencing signals related to epithelial-mesenchymal transition (EMT)." (PMID 39610918, 2024).